LEP (leptin)
Diseases named in the same sentence as LEP in open-access papers (continued):
Sharing a sentence is not in itself a finding about the gene and the disease.
Obesity (continued). "Leptin expression is increased in allergic asthmatic airways, and seems play a role in the relationship between asthma and obesity." (PMID 23383125, 2013). "In support of this, it has been reported that obesity reduced the vascular adrenergic reactivity by a sympatho-mediated leptin-specific mechanism." (PMID 23593350, 2013). "Over the past 15–20 years, mutations in a number of genes including leptin (LEP), leptin receptor (LEPR), pro-opiomelanocortin (POMC) and melanocortin-4 receptor (MC4R) have been associated with monogenic obesity." (PMID 23306188, 2013). "In line with progressive obesity, Ugcgf/f//CamKCreERT2 mice show indeed elevated leptin levels 7 wk p.i.." (PMID 23554574, 2013). "The circulating levels of several adipocytokines, such as TNF-α, IL-6, MCP-1, leptin, and PAI-1, are elevated in obesity and are reduced with weight loss." (PMID 23690838, 2013). "Based on the central action of leptin, it has been suggested that administration of leptin in the brain is more specific if it was used to treat obesity." (PMID 24023638, 2013). "This seminal work revealed robust differences in the gut communities of these mice compared with lean mice, both in the case of genetically induced obesity in the ob/ob leptin model and in diet-induced obesity." (PMID 23483075, 2013). "Recent studies suggest a protective effect of neonatal leptin supplementation against subsequent diet-induced obesity." (PMID 23423541, 2013). "Leptin-knockout mice have excess weight gain and have been used as an in vivo model of human obesity." (PMID 23957291, 2013). "Circulating leptin levels serve as an adiposity sensor to protect against starvation and correlate with the degree of obesity." (PMID 23356701, 2013). "Following the onset of obesity, mutant mice develop insulin resistance, increased glucose tolerance, and changes in blood biochemistry such as increased leptin, adrenocorticotropic hormone and insulin levels." (PMID 23649822, 2013). "Recent work in investigating the utility of combinational therapies for the treatment of obesity has focused on the coadministration of amylin with leptin." (PMID 24381591, 2013). "Studies in mice are consistent with the concept that leptin is an important contributor in the normal linkage between metabolism and alveolar ventilation in obesity." (PMID 23408476, 2013). "There is also a recent human ex vivo cell-based study that supports a role for leptin in obesity-related asthma." (PMID 24288549, 2013). "Leptin seems to be a promising biomarker also for OA patients, due to its involvement in disease pathogenesis and obesity." (PMID 24376307, 2013). "Obesity-induced chronic inflammation also induces leptin resistance through the activation of TLR4, JNK, and IKKβ." (PMID 23781214, 2013). "Here, we have demonstrated that removal of subcutaneous adipose tissue can be detrimental because obesity-induced increases in portal insulin and leptin concentrations following removal are exacerbated in mice that underwent this procedure." (PMID 23914298, 2013). "In this study indeed, desacylated ghrelin levels are decreased in human obesity, whereas leptin levels are increased, and the effects of desacylated ghrelin on energy homeostasis are opposite to those of leptin and acylated ghrelin." (PMID 24371438, 2013). "The ability of these hormones to decrease leptin levels thus suggests one mechanism for the known correlation with blood pressure in obesity." (PMID 24137236, 2013). "This strategy is particularly compelling as the activity of these autoinhibitory factors is increased in obesity, hinting at an etiological role for them in leptin resistance." (PMID 23092275, 2013). "Intranasal leptin induces significant weight loss and reduction of adipose tissue mass in lean and diet-induced obesity rats, which is consistent with the results of central leptin administration." (PMID 23579596, 2013).
Obesity (continued). "In fact, many authors have reported that HFD causes cardiac steatosis in genetically engineered models of obesity dealing with either generalized leptin resistance or aleptinemia." (PMID 24298268, 2013). "Low adiponectin status has been reported to be associated with obesity, MetS, and CVD, while high leptin or leptin resistance status has been reported to be associated with obesity, MetS and CVD." (PMID 23555948, 2013). "We previously showed that the adipose-tissue-derived hormone leptin, which is increased in obesity, favors the development of Th1 over Th2 T cells and is important in T cell development and survival." (PMID 23562076, 2013). "WNIN/Ob is leptin resistant with unaltered leptin or its receptor coding sequences - the two well-known candidate genes for obesity." (PMID 24204914, 2013). "High concentrations of plasma leptin and the release of pro-inflammatory cytokines in leptin-resistance in obesity have been reported to trigger endothelial dysfunction." (PMID 23856194, 2013). "Recent studies have shown that modulation of the autophagy pathway in specific hypothalamic neuronal populations leads to the development of metabolic dysfunction such as obesity and leptin resistance." (PMID 24376631, 2013). "Increased circulating adipose factors like leptin and the renin–angiotensin system, which are classically shown to mediate obesity-induced hypertension in rabbits or classically salt-resistant rats, do not seem to play a role in our HFD model." (PMID 24400139, 2013). "Some genetic loci for obesity have been identified, including several energy homeostasis-related peptide hormones, such as leptin, cocaine-amphetamine-regulated transcript (CART) and ghrelin." (PMID 24023638, 2013). "Modifications in the relative proportions of the lymphocyte classes depend on the degree of obesity, or on leptin concentration, or even fat depot anatomical location." (PMID 23634778, 2013). "Rats with overiectomy or deletion or siRNA-mediated silencing of estrogen receptor-α in the hypothalamus develop leptin resistance that attenuates leptin signaling in the hypothalamus and results in obesity." (PMID 24319483, 2013). "Fat removal, however, as an independent procedure exacerbated obesity-induced increases in leptin and insulin concentrations." (PMID 23914298, 2013). "In lean mice, leptin treatment that results in serum leptin concentrations consistent with those observed in obesity, increases inflammatory responses to acute ozone exposure." (PMID 24288549, 2013). "Coding DNA sequences of the known genes of obesity like leptin and leptin receptor seems to be unaltered in this animal model." (PMID 24204914, 2013). "Overall, we found BMI, universally used as proxy indicator of general obesity, had a satisfactory performance to correlate with leptin, especially in men." (PMID 23349940, 2013). "Metabolic dysfunction with obesity and insulin as well as leptin resistance can be observed in genetic models of HD expressing human full-length htt, such as the YAC and BACHD mice." (PMID 24376631, 2013). "Another potential mechanism to explain stress-induced endothelial dysfunction in obesity is the interactions of leptin with oxidative stress and inflammation." (PMID 24223557, 2013). "Leptin regulates food intake via brain signaling of satiety and energy store levels and is paradoxically increased in obesity, with obese individuals appearing to be resistant to the effects of leptin." (PMID 24072088, 2013). "Further studies are necessary for the clinical use of the leptin therapy, and leptin gene therapy is expected to be an effective therapeutic option for obesity, diabetes, depression." (PMID 23579596, 2013). "Other factors should be sought for a better understanding of the connection between serum leptin and adiponectin levels with obesity and asthma controls." (PMID 24454412, 2013).
Obesity (continued). "It is therefore, interesting to examine if blockade of leptin function (e.g., by inhibitors to OBRs) will modify the effect of obesity on LDD development in vivo." (PMID 23335226, 2013). "Numerous publications suggest leptin as a biomarker for obesity, insulin resistance and Metabolic Syndrome in adults." (PMID 23271695, 2013). "Plasma leptin levels are seen to be elevated in obesity and correlate positively with both visceral and subcutaneous fat areas." (PMID 24347825, 2013). "A better understanding of the neural circuits by which leptin regulate body weight is essential to develop new strategies for the treatment of obesity." (PMID 23527232, 2013). "Leptin at levels corresponding to obesity (100 ng/ml) and pharmacological concentrations (1 000 ng/ml) enhanced VEGF expression in MCF7 and MDA-MB-231 cells." (PMID 23554900, 2013). "Decreased sensitivity to peripherally administered leptin can occur in mice with diet-induced obesity that have very high (e.g. ten-fold elevated) leptin levels even in the absence of a genetic mutation." (PMID 23341784, 2013). "Although leptin in serum was increased in obesity T2DM rats, PF40 groups display reduced significantly it." (PMID 24131482, 2013). "In the arcuate nucleus, enhanced PIP3 signaling and increased KATP channel activity in POMC neurons led to hyperphagia and diet-induced obesity at least in part by blunting the acute effects of leptin and insulin." (PMID 23734095, 2013). "Taken together, the data indicate that leptin induced augmentation of the inflammatory response to ozone requires increases in serum leptin above those normally observed in lean mice, that is, increases such as those observed in obesity." (PMID 24288549, 2013). "Nevertheless, before establishing a possible cause-and-effect relation among leptin, TNF-α, and IL-12 in the scenario of obesity, additional prospective clinical research is required." (PMID 23986664, 2013). "Long-term increases in leptin or insulin lead to receptor desensitization and insulin or leptin “resistance” increasing plasma glucose levels and fat accumulation, producing eventually obesity and diabetes." (PMID 23781199, 2013). "Since the discovery of leptin, leptin has been taken for its therapeutic potential to obesity and diabetes." (PMID 23579596, 2013). "Circulating levels of leptin are increased in obesity and have been proposed to contribute to the development of hypertension in obese individuals." (PMID 24137236, 2013). "Since visceral adiposity is positively correlated to plasma leptin concentration, the circulating leptin level is an ideal indicator for assessing obesity in both experimental animals and humans." (PMID 23401719, 2013). "The physiological, metabolic and pro-inflammatory role of different adipokines, such as, leptin, resistin, visfatin will be discussed individually and according to the role each plays in diabetes, obesity, and immunity." (PMID 23634778, 2013). "A similar paradoxical effect is observed for e.g. leptin, which counteracts obesity but still is increased in obese subjects." (PMID 23360456, 2013). "Since leptin regulates body fat stores through its effects on food intake and energy metabolism, leptin is an important molecule in the obesity process." (PMID 23533517, 2013). "Insensitivity to peripheral leptin has been demonstrated in diet-induced and genetic models of obesity." (PMID 23341784, 2013). "This HD mouse model expresses full-length human htt with 97Q and develops obesity as well as insulin and leptin resistance." (PMID 24376631, 2013). "Serum leptin is proinflammatory that affects both innate and adaptive immune responses, and serum levels are markedly increased in obesity." (PMID 24454412, 2013). "Leptin and adiponectin, as adipocyte-derived hormones, play key roles in obesity and energy homeostasis." (PMID 23533517, 2013).
Obesity (continued). "Herein, we review the role of leptin in regulating feeding behavior and glucose metabolism and also the therapeutic potential of leptin in obesity and diabetes mellitus." (PMID 23579596, 2013). "Leptin, one of obesity relating factors, is an adipocyte-derived hormone important for fat metabolism, and leptin levels correlate with insulin resistance." (PMID 24023638, 2013). "In summary, the levels of leptin, adiponectin, oxLDL, CRP, and triglycerides in patients with T2DM seem to be more associated with obesity and less with diabetes." (PMID 24634792, 2013). "Deletion of leptin (ob/ob) or the leptin receptor (db/db), or administration of an HFD, in mice caused obesity and increased severity of pancreatitis." (PMID 24474939, 2013). "The suppressor of cytokine signaling (SOCS) protein inhibits the JAK-STAT pathway and leads to leptin resistance and obesity." (PMID 23634778, 2013). "Suppressor of cytokine signaling-3 haploinsufficiency in mice enhances the weight-reducing effects of leptin and confers resistance to diet-induced obesity." (PMID 23092275, 2013). "In the current study, levels of plasma adiponectin and leptin were examined in men with varying degrees of obesity that had marked interindividual variation in plasma triglycerides and insulin sensitivity." (PMID 23533722, 2013). "Plasma leptin is elevated during obesity, and cells of both the innate and adaptive immunity are influenced by leptin." (PMID 24098717, 2013). "Obesity appears to affect bone metabolism directly or indirectly through adipocyte-derived cytokines such as leptin and adiponectin." (PMID 24302863, 2013). "The ability of all four cardiac hormones to markedly decrease leptin levels was suggestive of a novel potential treatment target for hypertension in obesity, since these four cardiac hormones have demonstrated blood pressure-lowering properties." (PMID 24137236, 2013). "One of the mechanisms of increasing hypertension due to obesity is the hormone leptin which is derived from fat tissues and activates sympathetic nervous system." (PMID 24472511, 2013). "Leptin, a key hormonal regulator of appetite and metabolism, mainly secreted by adipocytes is thought to be the link between Tregs and obesity." (PMID 23936084, 2013). "It has been suggested that these high circulating levels of leptin in obesity function pathophysiologically for the development of hypertension." (PMID 24137236, 2013). "Investigators recently attempted the intranasal administration of leptin in rats with diet-induced obesity." (PMID 23579596, 2013). "First, the prevalence and severity of obesity in these cohorts were lower relative to the United States which truncates the high end of the range of systemic leptin concentrations studied." (PMID 24288549, 2013). "The finding that leptin deficiency in animals results in morbid obesity generated hope that exogenous administration of leptin would ameliorate obesity." (PMID 23092275, 2013). "Study in human showed that plasma ghrelin inversely correlated to degree of obesity and in this study, ghrelin reduced serum leptin level in obese mice." (PMID 23533447, 2013). "It was previously suggested to incorporate leptin adjustments into a more accurate diagnosis of obesity considering also that a significant decrease of leptin affects long-term weight control." (PMID 23662101, 2013). "To gain additional mechanistic insights on the cause of altered striatal DA homeostasis upon maternal overnutrition, we have turn to examine the consequent changes of central leptin signaling, a pathway frequently affected in obesity." (PMID 24223863, 2013). "As expected, significantly elevated plasma leptin and suppressed adiponectin, a typical adipokine phenotype of obesity, were shown in Class III obese subjects, as was the inflammatory profile of much higher levels of plasma hsCRP but lower IL10." (PMID 23342053, 2013).
Obesity (continued). "Our findings are in line with several studies reporting altered NK cell functions in obesity or after treatment with the adipokines leptin or adiponectin." (PMID 24098717, 2013). "The same treatment with pharmacological doses of leptin in early undernourished male pups conferred protection against obesity development, but only when animals were under HF diet." (PMID 24312379, 2013). "It has been shown that deficient ObR signaling due to leptin resistance of the Arc in mice with diet-induced obesity (DIO) is a consequence of long-term elevated leptin levels." (PMID 23554574, 2013). "The interactions between the brain melanocortin system and leptin represent an important area of research to further understand the mechanisms leading to SNS activation in obesity." (PMID 24288531, 2013). "Within this model, obesity is induced in both the C57BL/6J (B6) and the BTBR strains via introduction of the ob mutation (Lepob) into the leptin gene." (PMID 23860123, 2013). "Regarding leptin, the resistance to its effects has been proposed to explain the reduced activity found in obesity." (PMID 24634792, 2013). "Since the discovery of leptin, it has been expected the therapeutic potential for obesity and diabetes." (PMID 23579596, 2013). "Fasting leptin levels are remarkably elevated in adipocyte from obese individuals, and its gene expression is significantly increased in rats with diet-induced obesity." (PMID 23533517, 2013). "Leptin, the product of ob gene, is a peptide that is strongly correlated with adiposity and is a potential determinant of obesity and its complications." (PMID 23853613, 2013). "Levels of plasma triglyceride for each obesity category also were compared between men with low or high ratios of adiponectin/leptin." (PMID 23533722, 2013). "MCR1/CD68 ratio increased significantly after weight loss in parallel to adipogenic genes, such as FASN, ADIPOQ, IRS1 and SLC2A4, whereas LEP (an obesity gene marker) and IL6 (an inflammatory marker) decreased." (PMID 23951013, 2013). "Recent preclinical evidence has shown that coadministration of amylin with leptin improves leptin-mediated STAT3 signaling in the ventromedial hypothalamus of rats with diet-induced obesity." (PMID 23092275, 2013). "The findings provide experimental evidence supporting the benefit of leptin as a complementary therapeutic agent in the treatment of obesity and other related disorders." (PMID 24340098, 2013). "Lots of studies reported that a strong positive correlation exists between the concentration of leptin and insulin sensitivity and obesity, but the anti-insulin resistance effect of leptin, independently of its activity on weight control, was also reported." (PMID 23762871, 2013). "Several studies reported the in-vitro effects of leptin in proliferation of stem cells and WBC production and that leptin potentiates platelet aggregation and activation in obesity." (PMID 23617205, 2013). "As expected, our results show that circulating levels of leptin increase with obesity-related anthropometric parameters." (PMID 23986664, 2013). "Leptin is usually transported across the blood-brain barrier by a specialized leptin-transporter that is impaired in obesity." (PMID 23092275, 2013). "However, the low concentration of leptin in the milk of the SF dams might have led to suboptimal development of hypothalamic neurons involved in energy balance and predispose to offspring obesity." (PMID 23423541, 2013). "Obesity-induced alterations in adipocyte tissue result in altered expression or function of important endocrine hormones like leptin and adiponectin." (PMID 23533517, 2013). "Recently, a study reported the association of rs9939609 variant with high leptin levels suggesting the role of this SNP in inducing leptin resistance and disturbing the regulation of food intake and energy expenditure leading to obesity." (PMID 24102053, 2013).